GJA4 (gap junction protein alpha 4)
Description:
One gap junction consists of a cluster of closely packed pairs of transmembrane channels, the connexons, through which materials of low MW diffuse from one cell to a neighboring cell.
Synonyms: Cx37
Tractability: Antibody: its Gene Ontology location is reachable by antibodies, with high confidence; UniProt places it where antibodies can reach, with medium confidence; UniProt predicts a signal peptide or a membrane-spanning region.
Gene: Protein-coding gene on chromosome 1 (34,792,997 to 34,795,756, forward strand). Ensembl gene ENSG00000187513.
Subcellular location: Cell membrane; Cell junction, gap junction
Pathways (Reactome):
Vesicle-mediated transport: Gap junction assembly
Gene Ontology:
Molecular function: protein binding; gap junction channel activity
Biological process: cell-cell junction assembly; cell-cell signaling; cell communication; transmembrane transport
Cellular component: connexin complex; gap junction; plasma membrane
Genetic constraint (gnomAD): Loss-of-function variants: 13 observed, 26.4 expected, observed/expected ratio (o/e) 0.49, 90% interval 0.32 to 0.78. The upper end of that interval is the gene's LOEUF score, 0.78, which puts it in group 3 of 6, group 1 being the genes least tolerant of losing a copy. Missense variants: 357 observed, 456.03 expected, observed/expected ratio (o/e) 0.78, 90% interval 0.72 to 0.86. Synonymous variants: 167 observed, 199.36 expected, observed/expected ratio (o/e) 0.84, 90% interval 0.74 to 0.95.
Homologues: Orthologues: macaque GJA4 (99% identical), rabbit GJA4 (95% identical), dog GJA4 (95% identical), pig GJA4 (95% identical), guinea pig GJA4 (89% identical), mouse Gja4 (89% identical), rat Gja4 (89% identical), tropical clawed frog gja4 (64% identical), tropical clawed frog gja4.2 (52% identical), zebrafish gja4 (38% identical). Paralogues in human: GJA1 (49% identical), GJA3 (45% identical), GJA5 (42% identical), GJA10 (41% identical), GJA8 (41% identical), GJA9 (41% identical), GJC1 (36% identical), GJC2 (34% identical), GJB2 (32% identical), GJB1 (32% identical), GJB4 (32% identical), GJB6 (32% identical), and 8 more.